FGF2 (fibroblast growth factor 2)
Diseases named in the same sentence as FGF2 in open-access papers (continued):
Sharing a sentence is not in itself a finding about the gene and the disease.
Stroke (continued). "These limitations could be limiting factors to the development of FGF2 as a protective agent affecting multiple targets for the treatment of stroke, and should be carefully considered." (PMID 33967812, 2021). "In addition to being a neuroprotective agent in stroke, FGF-2 (a.k.a. basic fibroblast growth factor) can act as an angiogenic factor to promote sprouting and neurogenesis in stroke models." (PMID 30034335, 2018). "The potential for FGF-2 as a neurorestorative adjunct in stroke was first demonstrated in studies in which central administration of FGF-2 within 24 hr of MCAO induced improved motor recovery and the upregulation of growth-associated protein 43, a marker of axonal growth." (PMID 25229819, 2014). "Preclinical studies had demonstrated that application of FGF-2 before or within hours of stroke could reduce infarct size." (PMID 25229819, 2014). "Taken together these data suggest a scenario in stroke rehabilitation in which amphetamine-induced norepinephrine release can trigger the upregulation of FGF-2 which could contribute to the neural plasticity observed." (PMID 25229819, 2014). "Although the expression levels of FGF-2 appeared to be reduced in the hippocampus of the rats in the PSD group as compared with those in the stroke group, the decrease in the relative protein expression levels was not statistically significant (P>0.05; Student’s t-test)." (PMID 24944615, 2014). "Amphetamine plus physical therapy also significantly increased the number of FGF-2 expressing pyramidal neurons of the contralesional cortex at 2 weeks post-stroke and resulted in significant axonal outgrowth from these neurons at 8 weeks post-stroke." (PMID 25229819, 2014). "The present results support the hypothesis that enhanced noradrenergic activity induced by amphetamine upregulates FGF-2, which leads to enhanced axonal outgrowth and improved motor function following stroke." (PMID 25229819, 2014). "Therefore, for certain neurological diseases like stroke, exogenous administration of ADEVs containing FGF-2 and VEGF may hold therapeutic potential." (PMID 37728588, 2024). "Key EMT-related genes that were downregulated in MMP-3 KO males included Fbn1, Fbln1, Tgfb1, Tgfbr3, Snai2, and Fgf2, while female MMP-3 KO stroke brains showed downregulation of Fbln5, Fbln1, Fbln2, and Tgfb1." (PMID 39000490, 2024). "Neurotrophins were also developed as new treatments of acute stroke, and FGF-2 and EPO were administered as IV infusions within the first 5 h of the stroke." (PMID 35745855, 2022). "Stroke induced a significant increase in VEGFA, VEGFR2, FGF2, and FGFR1 expression 1–3 days after MCAO." (PMID 34992208, 2022). "Western blot analysis confirmed increased post-stroke cerebral angiogenesis in HMW-HA treated mice, as presented by higher expression of VEGFR, VEGF2, FGF2, and FGFR1 3 days following MCAO." (PMID 34992208, 2022). "The effect of giving basic fibroblast growth factor (bFGF), fibroblast growth factor 2 (FGF-2) and epidermal growth factor (EGF) after stroke is uncertain." (PMID 35756121, 2022). "In the studies with animal models of stroke, an increase in the expression of BDNF, GDNF, HGF, EGF, FGF-2, and IGF-1, as rapidly as 12 h after the insult and lasting until 5 days after stroke, has been described." (PMID 26607630, 2016). "The therapeutic potential of FGF21 in stroke has been indicated by studies in animal models; however, the main limitation for a future translational application is the side effects of other related factors, such as FGF2 and FGF23, in clinical trials with stroke patients." (PMID 35207221, 2022). "In addition to treating MI, growth factor/IgG complexes or FGF2/Fc-fusion complexes may be well suited to improve tissue survival and function after organ transplantation or to treat other forms of injury such as diabetic neuropathy, peripheral artery disease, chronic ulcer, and stroke." (PMID 35295649, 2022).
Stroke (continued). "Another factors identified after stroke and which might directly affect NSC proliferation are, among others, fibroblast growth factor-2 (FGF-2), insulin-like growth factor-1 (IGF-1) and brain-derived neurotrophic factor (BDNF)." (PMID 33834025, 2021). "By contrast, the reduction in the protein expression levels of FGF-2 in the hippocampus of the PSD group was not statistically significant when compared with the stroke group, although a slight decrease was observed (P>0.05; Student’s t-test)." (PMID 24944615, 2014).
glioblastoma (57 papers, 2008 to 2025). The most malignant astrocytic tumor (WHO grade IV). "The inhibition of FGF2 signaling has been associated with the suppression of glioblastoma cell proliferation and reduced angiogenesis in glioblastomas." (PMID 38892305, 2024). "FGF2 has also been implicated in glioblastoma multiform (GBM), a grade IV HGG, which also frequently overexpresses FGFR1." (PMID 37130917, 2023). "Fibroblast growth factor 2 encoded by the FGF2 gene is a crucial positive regulator of glioblastoma cell proliferation and survival." (PMID 36142793, 2022). "Because TAT-Cx43266–283 inhibits NPC growth promoted by EGF and FGF-2 via Src inhibition, this peptide might be used to target NPCs carrying mutations that lead to glioblastoma development." (PMID 33238452, 2020). "In this sense, the levels of VEGF and fibroblast growth factor 2 (FGF2) were shown to be significantly higher in patients with glioblastoma and associated with shorter overall survival rate, demonstrating the usefulness of these proteins as potential diagnostic and prognostic biomarkers." (PMID 31284524, 2019). "In glioblastoma cases, specifically, increased levels of both FGF2 mRNA and proteins have been reported through Northern blotting, immunohistochemistry, and in situ hybridization." (PMID 40141406, 2025). "Glioblastoma cells secrete FGF‐2 when in contact with BBB in vitro, strengthening barrier properties." (PMID 39101628, 2024). "FGF2‐induced downstream signaling mediated via FGFR1 has been shown to induce glioblastoma radioresistance through its downstream effector PLCγ,36 indicative a potential role of FGFR1 in modulating normal cell radiosensitivity." (PMID 36051984, 2022). "The FGF2 role in malignant glioma is proven and tagged FGF2, a novel druggable target, is used for developing potent drugs against glioblastoma." (PMID 36505741, 2022). "In human glioblastoma multiforme, FGF2’s nuclear import promoted the proliferation and survival of cancer cells." (PMID 36059652, 2022). "Secretion of FGF2 by glioblastoma cells enhances the blood–brain barrier function of endothelial cells, contributing to drug resistance." (PMID 34127812, 2021). "Among the key signaling elements that mediate receptor-initiated signaling in regulating glioblastoma invasion, there are Rho family GTPases, but FGFs play also their role, as in the case of basic fibroblast growth factor (FGF2, also called bFGF)." (PMID 33352931, 2020). "The involvement of small proteins like mTORC1, metalloproteases, FGF-2 and NF-kB promotes tumor growth and invasion by enduring glioblastoma stem cells, thereby promoting angiogenesis." (PMID 29149079, 2017). "Soluble VEGFR-1 (sVEGFR-1), but not sVEGFR-2, -3, and basic fibroblast growth factor (bFGF, alternatively known as FGF-2), have been reported to be increased in pre-operatively collected serum samples from newly diagnosed glioblastoma patients." (PMID 25720744, 2015). "Previous study demonstrated that high FGF2 mRNA expression is observed in over 94% of human glioblastomas." (PMID 26056081, 2015). "It is well documented that FGF2 enhances glioblastoma stem cell renewal." (PMID 36505741, 2022). "Inhibition of FGF using the small-molecule multi-FGF receptor blocker SSR128129 radiosensitizes human glioblastoma, indicating that targeting of the FGF2–FGFR pathway might be of interest when aiming to radiosensitize human glioblastoma." (PMID 34127812, 2021). "A study on hsa-miR-302d-5p and glioblastoma showed that hsa-miR-302d-5p could function as a tumor inhibitor inhibiting glioblastoma via targeting NF-κB as well as FGF2." (PMID 33323543, 2020). "Note: Other stemness-related genes such as nanog, oct4, FGF2, and others also get upregulated in GBM and contribute to the stemness in glioblastoma oncogenesis." (PMID 35538578, 2022). "Thus, precise targeting of the FGF2 signaling pathway can improve glioblastoma therapeutics." (PMID 36505741, 2022).
glioblastoma (continued). "Considering the major role of FGF2 in glioblastoma occurrence and development, the protein may serve as an excellent druggable target against glioblastoma, and drug designing against this target may stop glioblastoma." (PMID 36505741, 2022). "In another study, freshly resected glioblastoma multiforme cells were grown in a special serum-free medium supplemented with EGF and FGF-2 or PDGFA alone." (PMID 38392188, 2024). "Considering that FGFR1 regulates GBM differentiated cells radioresistance and the primordial role of FGF2 in GSC maintenance, we investigate here whether FGFR1 may regulate glioblastoma stem-like cells (GSLC) radiosensitivity." (PMID 30167084, 2018). "Moreover, in the serum of patients with glioblastoma (the most typical parenchymal brain tumor), it has been reported that there is a significant overexpression of IL-6, IL-1β, TNF-α, IL-10, VEGF, FGF-2, IL-8, IL-2, and GM-CSF." (PMID 37368708, 2023). "In accordance with this, in glioblastoma patients treated with VEGFR inhibitors, an increase of FGF-2 levels was observed in correlation with tumor progression, suggesting that targeting FGF could be part of the treatment for glioblastomas resistant to anti-VEGF therapy." (PMID 35269788, 2022).
myocardial infarction (57 papers, 2008 to 2026). Gross necrosis of the myocardium, as a result of interruption of the blood supply to the area, as in coronary thrombosis. "Fibroblast growth factor 2 (FGF2) plays a crucial role in cellular proliferation, differentiation, and survival and has been implicated in the development of various vascular diseases, including myocardial infarction, atherosclerosis, and pulmonary hypertension." (PMID 41292702, 2025). "Studies have demonstrated that increased low molecular weight FGF2 expression in cardiac tissue mitigates post-ischemic systolic dysfunction and reduces the severity of myocardial infarction in mice." (PMID 41292702, 2025). "In an ischemia−reperfusion injury model, overexpression of Fgf2 restores cardiac contracting rate and minimizes myocardial infarct size." (PMID 34095143, 2021). "Hi-FGF2 elicited hypertrophy following myocardial infarction, but Lo-FGF2 protected cardiomyocytes from damage." (PMID 32354131, 2020). "It was also reported that FGF1 and FGF2 expression was increased following myocardial infarction in rats." (PMID 31149027, 2019). "Basic fibroblast growth factor (FGF2) is reported to have protective roles of myocardial infarction as well as in several other I/R related disorders." (PMID 28544332, 2017). "In contrast, FGF2 knockout mice subjected to cardiac ischemia-reperfusion injury have significantly increased myocardial infarct size and worsened cardiac function, indicating that FGF2 protects cardiac ischemia-reperfusion injury." (PMID 27803896, 2016). "Increased expression of human FGF2 has been shown to reduce postischemic cardiac dysfunction and myocardial infarct size through activation of protein kinase C (PKC), mitogen‐activated protein kinase (MAPK), and nitric oxide signaling." (PMID 25626875, 2015). "Consistent with known increases in Fgf2 expression following myocardial infarction, Fgf2 mRNA levels were significantly increased in wild‐type hearts at 7 days after IR injury in both the IR area and the remote area of the left ventricle (P < 0.05)." (PMID 25626875, 2015). "Cardiac hypertrophy and fibrosis were less developed in Fgf2 knockout mice with myocardial infarcts." (PMID 23600527, 2013). "Similarly, FGF2-immobilized matrix-assisted hASC spheroids have been shown to effectively reduce the size of myocardial infarction and inhibit apoptosis of cardiomyocytes by upregulating in vivo neoangiogenesis." (PMID 37644502, 2023). "The protective role of FGF2 against I/RI is best documented for myocardial infarction." (PMID 28544332, 2017). "However, myocardial infarct-induced cardiac hypertrophy and fibrosis are protected against in FGF2 knockout mice." (PMID 27803896, 2016). "In addition, future therapeutic use of FGF2 for acute myocardial infarction would likely focus on activation of FGF2 signaling during reperfusion of the myocardium." (PMID 25626875, 2015). "This is particularly relevant for tissue repair following myocardial infarction (MI), where FGF-2 supports the formation of new blood vessels in damaged myocardial tissue." (PMID 40630127, 2025). "As melatonin appears to participate in the healing of myocardial infarction and it exerts profibrotic effects, we hypothesize that induction of FGF-2 synthesis alleviates melatonin-dependent collagen deposition and protects the heart from severe fibrosis development." (PMID 37188903, 2023). "Additionally, cardiac‐specific overexpression of human FGF2 results in decreased postischemic cardiac dysfunction and myocardial infarction, whereas ablation of the Fgf2 gene results in worsened postischemic outcomes in an ex vivo work‐performing murine model of global IR injury." (PMID 25626875, 2015). "For example, after myocardial infarction, rat BMSCs secrete paracrine factors (TGF-β, FGF-2, angiopoietin-2, VEGF-1) to trigger angiogenic and migratory effects at the site of the infarct to promote myocardial healing and improve the cardiac function." (PMID 31357692, 2019).
myocardial infarction (continued). "RADA in particular has been demonstrated to improve myocardial infarction when combined with either platelet-derived growth factor-BB (PDGF-BB) or with a combination of PDGF-BB and fibroblast growth factor-2 (FGF-2)." (PMID 30008751, 2018). "Systemic administration of FGF2 following acute myocardial infarction in rats induced significant hypertrophy in non-infarcted myocardium." (PMID 24349409, 2013). "Fibroblast growth factor 2 (FGF2) is cardioprotective in in vivo models of myocardial infarction; however, whether FGF2 has a protective role in in vivo ischemia‐reperfusion (IR) injury, a model that more closely mimics acute myocardial infarction in humans, is not known." (PMID 25626875, 2015). "In particular FGF1, FGF2, and the herein not analysed FGF4 show promising results in clinical trials to improve angiogenesis after myocardial infarction or angina pectoris." (PMID 39940657, 2025). "These suggest Lo-FGF2 (18 kDa), regulating cell survival, angiogenesis and ECM remodelling, has great potential in myocardial infarction treatment rather than Hi-FGF2." (PMID 36102060, 2022). "In addition, administration of rat Hi-FGF-2, but not Lo-FGF-2 after myocardial infarction promoted cardiomyocyte and cardiac hypertrophy; in the same model, rat Lo-FGF-2, but not Hi-FGF-2, was capable of sustained cardioprotection and angiogenesis after myocardiac infarction." (PMID 24827991, 2014).
colon carcinoma (55 papers, 1992 to 2025). "Overall, our findings indicated that strong interconnections among the 282 MDGs in colon cancers, with IL-10 and FGF2 acting as core genes that are closely linked to tumor angiogenesis and anti-tumor immune response." (PMID 38327746, 2024). "For instance, fibroblast growth factor 2 (FGF2) has been shown to promote chemoresistance in colon cancer cells via activation of the PI3K/Akt pathway." (PMID 41404422, 2025). "We measured levels of basic fibroblast growth factor (FGF-2) in human colon cancer cells (clone A) in vitro and in xenografted solid tumours using a commercial enzyme-linked immunoassay." (PMID 7599036, 1995). "Furthermore, FGF7 or FGF2 suppressed the expression of some ISGs in human lung epithelial cells, colon cancer cells (this study), or in human astrocytes, respectively." (PMID 32720440, 2020). "Recently, it was shown that CAFs led migration of colon cancer cells via surface associated FGF-2, which binds to the FGFR located on the surface of cancer cells, activating SRC and inducing integrin αvβ5 expression which leads to adhesion of colon cancer cells to fibroblasts." (PMID 27929432, 2016). "Indeed, we show FGF-BP knockdown was able to abolish the stimulatory effects of exogenous FGF2 in colon carcinoma cells." (PMID 22111880, 2011). "In addition, colon cancer spheres require ultra-low-attachment conditions, epidermal growth factor and fibroblast growth factor-2, plus culture for 4 weeks, whereas colospheres form in 1 day, without adding exogenous growth factors." (PMID 19603013, 2009). "FGF2 also induces EMT in many types of cells, such as Hertwig’s epithelial root sheath (HERS) cells, renal tubular cells, colon cancer cells and PCa cells." (PMID 26650737, 2015). "Mulitple molecules such as ADAM-10, ADAM-17, MMP-7, MMP-9, MMP-14, and bFGF/FGF2 increase SDC1 shedding in multiple myeloma as well as breast and colon cancers." (PMID 26293675, 2015). "Growth factors and receptors FGF2, IGF1R, PDGFRB and TGFA were identified as factors contributing selectively to the control of U2OS osteosarcoma and HCT116 colon cancer cell growth." (PMID 24023735, 2013). "Remarkably, growth factors and receptors FGF2 and IGF1R were identified as common, and PDGFR and TGFA as specific factors contributing to U2OS human osteosarcoma and HCT116 colon cancer cells growth, respectively." (PMID 24023735, 2013). "For instance, FGF1 and FGF2 have been shown to promote migration of intestinal epithelial cells, and specific isoforms of FGFR3 can mediate growth and migration of colon cancer cells." (PMID 21853123, 2011). "A previous publication showed that administration of basic fibroblast growth factor (FGF-2, 0.25 mg kg-1, q.i.d. x 7) to mice bearing xenografted DLD-2 human colon cancers would increase treated tumour growth rates as compared to control neoplasms." (PMID 8398700, 1993). "In colon carcinoma, ANGPT2 and VEGF‐A expression is significantly higher (P < 0.0001) in the tumor compared to the adjacent normal colon, whereas expression of ANGP1, PDGFA, and FGF2 is significantly lower (P < 0.0001)." (PMID 34102002, 2021). "An increased activity of autocrine/paracrine FGF2/FGFR-mediated loops were proofed for the multiple types of malignancies, including endometrial, bladder, non-small cell lung cancer, breast, multiple myeloma, prostate, gastric and colon cancers." (PMID 31948066, 2020). "While this secretion is comparable to that of the colon cancer CTC cell line CTC‐MCC‐41, CTC‐ITB‐01 does not secrete OPG (osteoprotegerin), EGFR (epidermal growth factor receptor) or FGF2 (fibroblast growth factor‐2) characteristic for CTC‐MCC‐41." (PMID 32667137, 2020). "In patients with colon carcinoma (n = 262), high ANGP2 and VEGF‐A expression, individually, predicts a somewhat worse probability of survival compared to low ANGPT2 or VEGF‐A expression, whereas high or low ANGPT1, PDGFA, and FGF2 expression has no impact." (PMID 34102002, 2021).